STK11 (serine/threonine kinase 11)
Diseases named in the same sentence as STK11 in open-access papers (continued):
Sharing a sentence is not in itself a finding about the gene and the disease.
lung cancer (continued). "In our previous study of lung cancer whole-genome sequencing using Illumina, we noticed a possible local copy-number lesion in the STK11 gene region in RERF-LC-KJ cells." (PMID 32887687, 2020). "Hence, the STK11 mutation may serve as a novel biomarker for treating lung cancers for CGs." (PMID 32784680, 2020). "A recent study of young patients with nonsmall cell lung cancer showed that higher frequency of ALK and HER2 genetic alterations were associated with young age, while, mutations in KRAS, STK11, and EGFR exon 20 are more common in older patients." (PMID 32657049, 2020). "Patients with metastatic, KRAS-mutated lung cancer, treated with at least one cycle of a PD-1 inhibitor or an anti-PD-1/PDL-1 and anti-CTLA-4 combination regimen, had STK11/LKB1 mutations largely drive the primary resistance to PD-1 blockade, in any regimen." (PMID 32258034, 2020). "On the other hand, several CGs such as digoxin, digitoxin and ouabain were known to inhibit lung cancer progression by hindering the expression of α-1 subunit and exhibited discriminatory antitumor effects in STK11 mutant lung cancer cells." (PMID 32784680, 2020). "LKB1, also called STK11, plays an important role in lung cancer, mainly through the AMPK pathway, to regulate cell proliferation, metabolism, apoptosis, cell polarity, and cell epithelial transformation." (PMID 30185829, 2018). "As a second case study, we examined an ESP associated with aggressive lung cancer, mutated in 22% of lung tumors and involving mutations to the genes CYLC2, STK11 and STK11P." (PMID 30297789, 2018). "In support of this notion, lung cancer cells with reduced STK11 appear to be more sensitive than STK11 wild-type cells to palbociclib." (PMID 28205554, 2017). "This mechanistic relationship would nominate STK11 mutant lung cancer for therapeutic intervention with CDK4 inhibitors." (PMID 28205554, 2017). "Endogenous co-immunoprecipitation experiments demonstrated the STK11/CDK4 interaction under physiological conditions in multiple lung cancer cell lines, including H1299 and H1792 cells." (PMID 28205554, 2017). "Inhibition of ATPase Na+/K+ Transporting Subunit Alpha 1 (ATP1A1) was recently investigated by treating STK11 mutant lung cancer cells with CGs." (PMID 29117117, 2017). "In a mouse model of KRAS-driven lung cancer, co-mutation of LKB1/STK11 was shown to promote neutrophil recruitment and proinflammatory cytokine production, suggesting an additional mechanism of immune evasion." (PMID 29064420, 2017). "Inhibition of ATP1A1 using CGs warrants exploration as a targeted therapy for STK11 mutant lung cancer." (PMID 27431571, 2016). "In vitro validation confirmed that restoring STK11 function decreased the cellular response to CGs in a wide variety of STK11 mutant lung cancer cell lines." (PMID 27431571, 2016). "We then analyzed these same lung cancer datasets irrespective of driver mutation status, grouping samples solely by STK11-WT or STK11-mutant status." (PMID 40715535, 2025). "PEBP1 and STK11 transcript levels were associated with immunosuppressive properties and responses to immune checkpoint blockade (ICB) therapies, such as anti-PD1 and anti-CTLA4, particularly in melanoma, kidney, and lung cancers." (PMID 40806276, 2025).
lung cancer (continued). "However, we note that research on ENO3 is relatively few, with existing studies mainly focusing on its overexpression and selective anticancer activity in STK11-mutant lung cancer." (PMID 40464853, 2025). "Recently, we could show that the co-mutations of KRAS + KEAP1, STK11 + KEAP1 and KRAS + STK11 + KEAP1 lead to a significantly shorter median overall survival (mOS) in patients with lung cancer across treatments by analyzing multiple dataset." (PMID 39156705, 2024). "Furthermore, long intergenic non-protein coding RNA 473 (LINC00473) is upregulated by the inactivation of serine/threonine kinase 11 (LKB1), enhancing the proliferation of LKB1-inactivated lung cancer cells." (PMID 38398086, 2024). "For instance, both mutation and high amplification could be detected in EGFR, MET, and ERBB2 in lung cancer, as well as mutations in KRAS, BRAF, STK11, KEAP1 and many others." (PMID 39289779, 2024). "Third, the paraffin tissue related to STK11 detection was selected in early-stage and locally advanced lung cancer, the reason for which is that many metastatic lung cancers do not have the opportunity of surgery, and similar paraffin tissue cannot be obtained." (PMID 38736875, 2024). "Autophagy is activated in serine/threonine kinase 11 (STK11) mutant lung cancer." (PMID 38431606, 2024). "Additionally, we previously demonstrated that combinatorial treatment with metformin and pembrolizumab enhanced anti-tumor immunity in STK11 mutant lung cancer via axis inhibition protein 1 (AXIN1)-dependent inhibition of STING ubiquitination." (PMID 39308524, 2024). "STK11/KEAP1 co-mutations lead to a notable increase in the expression of ferroptosis-protective genes, including SCD and AKR1C1/2/3, as well as resistance to drug-induced ferroptosis in lung cancer cells." (PMID 37728413, 2023). "For instance, STK11 inactivation triggers EMT in lung cancer cells by inducing ZEB1 expression." (PMID 37506141, 2023). "Similarly, in the mouse, STK11, which was most commonly altered in lung cancer, appeared as the topmost gene on chromosome 19." (PMID 37626695, 2023). "STK11 and KEAP1 have been associated with a poorer prognosis in KRAS mutant lung cancer." (PMID 38067288, 2023). "In one study on the clinical outcome of pembrolizumab versus chemotherapy in lung cancer patients, it was observed that the treatment outcomes appeared to be comparable irrespective of the presence of STK11, KEAP1, or KRAS mutations." (PMID 38136385, 2023). "Moreover, silencing circHIPK3 results in the reduction of cell proliferation, migration invasion, and promotion of macroautophagy/autophagy via MIR124-3p-STAT3-PRKAA/AMPKα signaling in STK11 mutant lung cancer." (PMID 36338714, 2022). "Metformin could prevent acquired resistance to cisplatin in STK11 mutant lung cancer through reducing the number of tumor-initiating cells." (PMID 35281267, 2022). "However, more clinical trials with longer follow-up times are required to better understand the long-term benefits of targeted therapies in patients with STK11/LKB1 mutant lung cancer." (PMID 35165542, 2022). "Therefore, AXIN-1-based STING stabilization was required for metformin to activate STING pathway and enhance immunotherapy efficacy in STK11 mutant lung cancer." (PMID 35281267, 2022).
lung cancer (continued). "In serine/threonine kinase 11 (STK11)-deficient LUAD, YAP directly stimulates downstream effector surviving to promote malignant progression, and YAP overexpression in the KrasG12D lung cancer mouse model accelerates tumor progression." (PMID 34765600, 2021). "Liver kinase B1 (LKB1), which is encoded by serine/threonine kinase 11 (Stk11), is a tumor suppressor and its inactivation has been demonstrated to drive the development of lung cancer, melanoma, prostate cancer, and cervical cancer." (PMID 34921639, 2021). "Recent researchers found the knockdown of ENO3 exhibits anticancer effect in STK11 mutant cells and suggest that ENO3-based targeted therapy might be promising for lung cancer patients harboring STK11 mutations." (PMID 33747908, 2021). "Indeed, studies have shown that STK11/LKB1 inactivation in lung cancer cells led to an upregulated mTOR signaling providing growth advantages associated with mitochondrial dysfunction by autophagy impairment." (PMID 34831355, 2021). "In addition, there were reports that KRAS-driven lung cancer often inactivated STK11/LKB1 and responded poorly to immunotherapy." (PMID 34239621, 2021). "Finally, we discuss recent data based on pre-clinical models and lung cancer cohorts analyzing the results of STK11/LKB1 alterations on the immune system and response or resistance to immune checkpoint inhibitors." (PMID 34831355, 2021). "In STK11 mutant lung cancer cell lines (A549 and H838), the miR124-3p-STAT3-PRKAA/AMPKa axis had been reported, which could regulate circHIPK3-induced cell autophagy." (PMID 33681194, 2021). "In serine/threonine kinase 11 (STK11) mutant lung cancer, circHIPK3 could modulate autography through miR-124-3p-STAT3-PRKAA/AMPKα signaling." (PMID 33163392, 2020). "KRAS is the most common driver mutation in lung cancer, and is highly co-occurrent with KEAP1 and STK11 mutations, NOTCH1 has a putative role in skin cancer, loss of PTEN is the most common genomic alteration in glioblastoma, and DNMT3A has been associated with leukemia and myelodysplasia." (PMID 32374727, 2020). "Moreover, in lung cancer, EGFR and MET mutations, oncogene fusions or STK11 inactivating mutations were associated with low response rates." (PMID 32708698, 2020). "All these results suggest that circHIPK3 is a key autophagy regulator and could be used as a potential target in STK11 mutant lung cancer." (PMID 33163392, 2020). "STK11 mutation is considered to be the major mutation for lung cancer progression, and direct therapy was not implemented due to the loss of function of STK11." (PMID 32784680, 2020). "Besides the newly acknowledged relevance of STK11 in lung cancer, this disease is characterized by other, well known genetic abnormalities, such as EGFR, BRAFv600E mutations, ALK, ROS, or RET rearrangements, as well as METexon14 mutations." (PMID 32258034, 2020). "The STK11 (LKB1) mutation is a major mediator of lung cancer progression and a targeted therapy has not been implemented because STK11 mutations cause loss of function." (PMID 29117117, 2017). "The observed positive correlation supports future testing of this hypothesis to examine a potential therapeutic strategy for treating lung cancer patients harbouring STK11 alterations with a CDK4 inhibitor such as palbociclib." (PMID 28205554, 2017). "Though this is intriguing, the role that ATF5 plays in promoting LKB1/STK11 mutant lung carcinomas is unknown." (PMID 29137451, 2017). "Although STK11 (LKB1) mutation is a major mediator of lung cancer progression, targeted therapy has not been implemented due to STK11 mutations being loss-of-function." (PMID 27431571, 2016).
lung cancer (continued). "Germline mutations in the LKB1 gene (also known as STK11) cause the Peutz-Jeghers Syndrome, and somatic loss of LKB1 has emerged as causal event in a wide range of human malignancies, including melanoma, lung cancer, and cervical cancer." (PMID 24086281, 2013). "Germline mutations in LKB1, also called STK11 (serine-threonine kinase 11), cause the autosomal dominant Peutz-Jeghers syndrome (PJS), which bestows an increased risk of developing a wide range of cancers, including lung cancer." (PMID 22928112, 2012). "Together with a case report of an individual with STK11/KRAS co-mutated advanced lung cancer with near complete response to pembrolizumab and platinum-doublet therapy, these data suggest that STK11 mutation should not be used as a strict exclusion criterion for immune checkpoint blockade in NSCLC." (PMID 39172022, 2024). "Thus, our study indicates that targeting specific nucleotide metabolites and tumor metabolism could provide a potential therapeutic strategy for STK11 mutant lung cancer." (PMID 39308524, 2024). "Consequently, in the absence of STK11, lung cancers harboring KRAS mutations not only gain a growth advantage due to the unrestrained signaling of mTOR but also exhibit mitochondrial dysfunction, resulting in aggressive behavior." (PMID 39046176, 2024). "Additionally, the silencing of STING leads to immune escape in STK11 mutant lung cancer, and CDNs such as cyclic dimeric adenosine monophosphate (c-di-AMP) can elicit immune responses, whether these nucleotide metabolites have similar effects are unknown." (PMID 39308524, 2024). "As STING activation is crucial for anti-cancer immune response, and we previously found that metformin enhanced the efficacy of immunotherapy in STK11 mutant lung cancer via AXIN1-based STING stabilization, whether the nucleotide compounds involved in the activation of STING were unknown." (PMID 39308524, 2024). "Interestingly, we found that STK11 mutation status in lung cancer did not correlate with increased dependency on KRAS." (PMID 37141389, 2023). "Importantly, somatic alterations in the STK11 gene have emerged as potential therapy targets in patients with non–small cell lung cancer (NSCLC), an approach that may also lead to novel therapeutic opportunities in PDAC." (PMID 38201484, 2023). "In addition, somatic mutations in STK11 are found in many spontaneous (i.e. non-inherited) cancers, especially in the commonest form of lung cancer, adenocarcinoma, where they occur in up to 20% of all cases." (PMID 36383046, 2022). "Thus, our study indicated that metformin in combination with PD-1 inhibitor may be a potential therapeutic approach for STK11 mutant lung cancer." (PMID 35281267, 2022). "Genetically engineered mouse models have shown that the loss of liver kinase B1 (LKB1, also known as serine/threonine kinase (STK11)) can lead to lineage plasticity and SCC transformation in Kirsten rat sarcoma 2 viral oncogene homolog (KRAS) mutant lung cancers." (PMID 34572868, 2021). "NFE2L2 activity is further enhanced by serine/threonine kinase 11 (STK11) and KEAP1 co-mutation, which induces expression of ferroptosis-protective genes, such as stearoyl-CoA desaturase (SCD) and aldo-keto reductase 1 C family 1/2/3 (AKR1C1/2/3) in lung cancer cells." (PMID 34742351, 2021).
lung cancer (continued). "In contrast to the results of TCGA4,5, we detected low mutational frequencies of STK11, NF1, and BRAF were detected in LUAD and low mutational frequency of KEAP1 in both LUAD and LUSC, indicating the special molecular characteristics of Chinese lung cancer patients." (PMID 33219256, 2020). "This dual mechanism may explain the absence of a clear association between STK11 alterations and prognosis in lung cancer." (PMID 26625312, 2017). "In addition, the distribution of mtdsRNA in mitochondria versus cytosol seemed to differ between lung cancer cell lines with KP and KL mutations, suggesting that NSCLC cells with loss-of-function mutations in the LKB1 (STK11) gene may have stronger activation of the IFN-1 pathway." (PMID 38955468, 2024). "We found eight genes relevant to lung cancer (PDGFRB, RET, KRAS, KEAP1, ROS1, STK11, MET and ALK), for which integrating clinical data with our TME features clearly improves the ability to predict mutations in these genes." (PMID 36131239, 2022). "These analyses indicate that two key regulators of the mTOR pathway, STK11 and PTEN, have different functions in lung cancer biology and that KRAS and PTEN are mutually exclusive." (PMID 33652656, 2021). "It was demonstrated that STK11/LKB1 downregulates CPS1 transcription via AMPK-mediated effects and that KRAS/STK11 mutant lung cancer cells upregulate expression of CPS1, allowing cell division and tumor development." (PMID 34831355, 2021). "This study applied a mouse model of lung cancer based on CRISPR/Cas9 technology to functionally address key regulators of the mTor pathway, STK11 and PTEN." (PMID 33652656, 2021). "This notion is also supported by a clear co-occurrence with STK11 and KRAS gene alterations with a suggested synergic role of these genes in enhancement of tumorigenesis and lung cancer progression." (PMID 32971994, 2020). "Demonstration of two selected PPIs, MYC/NSD3 and STK11/CDK4, under endogenous conditions in multiple lung cancer cell lines strongly supports the validity of the OncoPPi network data set for further examination." (PMID 28205554, 2017). "Interestingly, the cytokeratin AE1/AE3-stained xMD-procured lung carcinoma cells showed a 13-fold increase in KRAS mutation frequency (%) in comparison to the macrodissected heterogeneous cytospin (67.4% vs. 4.9%) and a 15-fold increase in the STK11 mutation frequency (%) (45.4% vs. 2.9%)." (PMID 26999048, 2016).